IGF1R (insulin like growth factor 1 receptor)
Diseases named in the same sentence as IGF1R in open-access papers (continued):
Sharing a sentence is not in itself a finding about the gene and the disease.
breast cancer (continued). "Both preclinical and clinical studies demonstrate that the IGF-1R is overexpressed and hyperphosphorylated across multiple breast cancer subtypes, thereby providing a mechanistic basis for its oncogenic contribution." (PMID 41157306, 2025). "A previous study from breast cancer showed HIF1α upregulated IGF1R expression, and promoted cancer cells proliferation, invasion and chemotherapy-resistance." (PMID 40290443, 2025). "IGF-1R plays a role in the development and progression of various solid tumors, such as Ewing sarcoma, nonsmall cell lung cancer, and some types of breast cancer." (PMID 40718626, 2025). "EGFR and IGF1R, which drive signaling pathways involved in breast cancer development and progression, were also included due to their known crosstalk with E2-ER signaling pathways." (PMID 41228316, 2025). "Specifically, it was revealed that miR-122 directly targets the 3′-UTR of IGF-1R in breast cancer cells and limits cell proliferation as well as tumor formation and progression." (PMID 41153350, 2025). "IGF1R amplification was rare (1.1% across ERBB2alt tumors) with a comparatively high prevalence in ERBB2amp breast cancer (2.7%)." (PMID 40178042, 2025). "Our research group has studied the role of IGF1R in the context of different molecular and histological subtypes of breast cancer." (PMID 39207954, 2024). "Conversely, in hormone-responsive MCF-7 luminal breast cancer cells, which are less migratory, IGF-1R was more evident at the plasma membrane and at cell-cell and cell-matrix contact points, as previously documented." (PMID 39608716, 2024). "It has been demonstrated that IGF-1R is abnormally elevated in approximately 50% of breast cancers and negatively correlates with patient prognosis." (PMID 38342894, 2024). "Patients with metabolic disorders (obesity, T2DM) demonstrate increased breast cancer mortality in association with an altered expression profile of both RAGE and the IGF (insulin growth factor)-1/IGF-1R (receptor) axis." (PMID 39830522, 2024). "Recently, SSTR2 and IGF-1R were reported to be expressed in breast cancer, and several clinical trials of SSAs for breast cancer have been conducted." (PMID 39238765, 2024). "A similar pattern of IGF-1R staining in invasive breast cancer tissues is reported in the Human Protein Atlas database." (PMID 39608716, 2024). "Datasets from basal-like breast cancer patients indicated a strong, positive correlation between IGF-1R protein expression and that of β1-integrin (ITGB1)." (PMID 39608716, 2024). "Having demonstrated a suppressive role for miR-770-5p in EGFR/HER2 signaling, we next explored the effect of miR-770-5p on IGF1R, the one which is another escape signaling in trastuzumab resistant breast cancer cells." (PMID 39051060, 2024). "CXCL1 knockdown in TAMs demonstrated a remarkable chemosensitizing effect on breast cancer xenografts, along with blockage of IGF1R/STAT3/HMGB1 signaling in vivo." (PMID 39394189, 2024). "Dietary supplementation with lycopene mitigated the growth of breast cancer cells by suppressing the activity of the insulin-like growth factor 1 receptor (IGF-1R) signalling pathway." (PMID 38883868, 2024). "In breast cancer, IGF-1R drives the occurrence of EMT (epithelial-mesenchymal transition) through FAK and NF-kappaB, which in turn helps cancer cells to invade and circulate for survival." (PMID 38342894, 2024). "Patients with high IGF1R expression tend to have shorter overall survival and a higher possibility of metastasis in various types of cancer, such as breast cancer, prostate cancer, and lung cancer." (PMID 38292328, 2024).
breast cancer (continued). "Recently, somatostatin receptor 2 (SSTR2) and insulin-like growth factor 1 receptor (IGF-1R) have been reported to be expressed in breast cancer, and several clinical trials of SSAs in breast cancer have been conducted." (PMID 39238765, 2024). "According to the TCGA PanCancer Atlas—Breast Invasive Carcinoma dataset, ITGB1 is strongly coexpressed with the IGF-1R in basal-like breast cancer patient tumor tissue." (PMID 39608716, 2024). "For this purpose, the authors utilized cBioportal to conduct survival analysis for breast cancer patients with altered Insulin-like Growth Factor 1 Receptor (IGF1R) signalling pathway." (PMID 38461268, 2024). "There has been a long-standing interest in targeting the type 1 insulin-like growth factor receptor (IGF-1R) signaling system in breast cancer due to its key role in neoplastic proliferation and survival." (PMID 39362991, 2024). "Previous studies have implicated crosstalk between ITGB1 and IGF-1R in response to IGF-1 stimulation, particularly in breast cancer and prostate cancer cells." (PMID 39608716, 2024). "miR-122 suppresses oncogenes and key signaling pathways, such as IGF-1R, which is commonly activated in breast cancer." (PMID 39590305, 2024). "WOKVAC is a plasmid-based DNA vaccine encoding epitopes from three breast cancer antigens: HER2, IGFBP2, and IGF1R." (PMID 38256137, 2024). "Dalotuzumab, an anti-insulin-like growth factor 1 receptor (IGF-1R) antibody, was evaluated in combination with ridaforolimus for various cancers, including solid tumors, endometrial cancer, and breast cancer." (PMID 38584599, 2024). "Anti-type-I insulin-like growth factor receptor (IGF1R) is a molecule that is often overexpressed in breast cancer and is essential for the proliferation, survival, and metastasis of breast cancer cells." (PMID 39771506, 2024). "Clinically, CXCL1 was shown to be an independent predictor of poor prognosis and to be positively correlated with IGF1R/STAT3/HMGB1 expression in breast cancer." (PMID 39394189, 2024). "CAF-derived IGF2 secretion activates IGF1R signaling in breast cancer cells by increasing the EMT as well as the in vitro and in vivo growth and migration." (PMID 38892104, 2024). "In this study, restoring of miR-770-5p regulated EGFR/HER2/IGF1R crosstalk signaling in HER2+ breast cancer cells." (PMID 39051060, 2024). "Among these genes, IGF1R exhibited the strongest significant correlation with prognosis in breast cancer patients." (PMID 37569854, 2023). "Similar to our results, FOXO proteins were negatively regulated by the IGF1R/PI3K/AKT signalling cascade in breast cancer cells, human brain microvascular endothelial cell IRI, rat spontaneous intracerebral haemorrhage, or mouse cerebral IRI models." (PMID 37985893, 2023). "IGF-1R is overexpressed in about 50% of breast cancers and plays a central role in cell growth, metastasis, and angiogenesis." (PMID 37623967, 2023). "IGF-1R is overexpressed in lung cancer, breast cancer, pancreatic cancer, colorectal cancer, and HCC." (PMID 36698167, 2023). "Previous studies demonstrated that ligand bound estrogen receptor (ER) alpha is required for rapid activation of the IGF1R signalling cascade in ER positive breast cancer." (PMID 36920947, 2023). "This suggests that the use of sCAR-T cells co-targeting IGF1R in addition to HER2 is a promising strategy for treating HER2+ breast cancers, showing enhanced cytotoxic activity and T cell activation in comparison to monospecific sCAR-T cells." (PMID 37046648, 2023). "A previous study revealed that cannabinoid receptors promote the chronic intermittent hypoxia-induced breast cancer metastasis via IGF-1R/AKT/GSK-3β." (PMID 36983855, 2023). "Previously, we have shown that IGF1R inhibition increases response to trastuzumab in HER2 positive breast cancer cells." (PMID 36920947, 2023).
breast cancer (continued). "In our study, we have shown that despite IGF1R and IR being expressed in all breast cancer subtypes including TNBC, in silico analysis demonstrated that neither IGFR1 nor IR expression are associated with outcome in this subtype." (PMID 36920947, 2023). "IGF-1R promotes breast cancer by altering the expression of proliferation and survival genes through the Ras/Raf/MAPK and PI3K/Akt signaling pathways." (PMID 36755926, 2023). "This included cetuximab (as in the breast cancer specific analysis), IGF1R and LCK inhibitors, all identified to modulate the SAC." (PMID 37707389, 2023). "Downregulation of IR by shRNA sensitised pancreatic and breast cancer cell lines, and pancreatic xenograft tumours, to IGF1R inhibition." (PMID 36920947, 2023). "IGF-1R protein, overexpressed and hyperphosphorylated in many breast cancer subtypes, contributes to invasion and metastasis via an increase in the proliferation rate of tumor cells and a decrease in the rate of their destruction." (PMID 36612320, 2023). "Most invasive breast cancers have insulin/IGF-1R signaling activation, and xentuzumab in combination with paclitaxel can effectively reduce metastasis incidence and metastatic burden in preclinical mouse models." (PMID 36755926, 2023). "Specifically, trastuzumab-resistant breast cancer cells exhibit crosstalk between IGF-1R and HER-2 signaling since IGF-1R physically interacts with HER-2." (PMID 38406785, 2023). "First, we show in vivo that CR reduces tumor grow, IGF1 levels, and decreases the transcript and protein levels of IGF1R in mammary tumors." (PMID 37686596, 2023). "The IGF1R gene is highly expressed in 9% of cancer cells, including lung adenocarcinoma, cutaneous melanoma, breast cancer, and colon adenocarcinoma." (PMID 38274107, 2023). "In a different approach to fighting cancer, breast-cancer-related epitopes targeting the insulin-like growth factor receptor (IGF-1R) were used to construct chimeric VLPs." (PMID 37623967, 2023). "Insulin/IGF1R signaling has significant implications for treatment of and survival following breast cancer." (PMID 37237509, 2023). "IGF1R signalling has been implicated in treatment resistance in breast cancer, whilst in TNBC, IGF1R has been associated with worse disease free survival." (PMID 36920947, 2023). "Breast cancer: Increased IGF1R expression contributes to anti-estrogen resistance in breast cancer in patients with high expression of estrogen receptor." (PMID 36830998, 2023). "Increased expression of IGF-1R has been reported in various cancers, including Ewing sarcoma, breast cancer, prostate cancer, pancreatic cancer, melanoma, and other tumor types, contributing to faster tumor progression and, in some cases, poor prognosis." (PMID 37834454, 2023). "Both the expression and signalling activation of the IGF1R pathway have been extensively studied in breast cancer." (PMID 36920947, 2023). "The clinical correlation of YAP and IGF-1R signaling with the overall survival (OS) of 7830 breast cancer patients was analyzed by KM plotter." (PMID 37081542, 2023). "In breast cancer, IGF-1R has also been shown to resist the effect of trastuzumab, an anti-EGFR/HER2 antibody, by inhibiting the SRC/FAK/FoxM1 signaling pathway." (PMID 37834454, 2023). "The insulin/IGF1R signaling pathway is observed to be activated in 75% of breast cancers and 87% of invasive breast cancers, respectively." (PMID 37237509, 2023). "Increased signaling via IGF-1R has been involved in a reduced response to trastuzumab in breast cancer cells in vitro." (PMID 38406785, 2023). "In this study, we used breast cancer PDX models to show that IGF-1R signaling regulates YAP expression and its localization." (PMID 37081542, 2023). "We then attempt to reconcile these observations in order to shed light on the seemingly contradictory roles for IGF1R in breast cancer with a focus on mammary gland biology and tumorigenesis." (PMID 35784559, 2022).
breast cancer (continued). "As with the CD8α-IGF1R model, the hyperplasia eventually developed into palpable mammary tumors with an average latency of 71-78 days." (PMID 35784559, 2022). "IGF-1R signaling is also reported to mediate trastuzumab-resistant HER2+ breast cancer cells through cell cycle modulation." (PMID 36291900, 2022). "Insulin receptor (IR) and insulin-like growth factor 1 receptor (IGF1R) have been extensively studied in both breast cancer and diabetes therapies." (PMID 35710446, 2022). "Subjecting mammary tumor-bearing mice to IGF-1R inhibitor and immune checkpoint blockade was sufficient to mimic the anti-tumor effect of fasting in lung cancer." (PMID 35186923, 2022). "Loss of LFNG can elevate Met/insulin-like growth factor 1 receptor (Igf-1R) signaling, which contributes to basal-like breast cancer (BLBC)." (PMID 35335147, 2022). "We then compared these modules to single cell gene expression analyses and phenotypes of mouse mammary tumors with reduced IGF1R signaling or expression in a tumor model of triple negative breast cancer." (PMID 36568144, 2022). "miR-630 has also been shown to target IGF1R (Insulin Like Growth Factor 1 Receptor) to influence response of breast cancer cells to HER2-targeting agents." (PMID 35248081, 2022). "We used anti-IGF-1R antibodies to assay for receptor expression on cell surface of breast cancer cells (MCF-7, MD-MB-231, T47D, SK-BR-3 and BT474) and neuroblastoma cells (LAN-1) by flow cytometry." (PMID 35399718, 2022). "Many clinical trials have tested the efficacy of IGF/IGF-1R inhibitors in improving responses to cytotoxic and hormone therapy in breast cancer patients." (PMID 36556357, 2022). "The fact that IR is not enriched in the CSC population, and that IGF-1 and IGF-2 are more effective regulators of CSC function than insulin, supports a dominant role for the IGF-1R in regulating breast cancer stemness." (PMID 36556357, 2022). "IGF-1R signaling decreases chemotherapeutic responses in breast cancer through multiple mechanisms, including promoting proliferation, enhancing cancer stemness, inhibiting apoptosis through DNA damage repair, and inducing efflux transporters." (PMID 36556357, 2022). "For example, in trastuzumab-resistant breast cancer cells, IGF-1R and HER-2 form a heterodimer, which can ligate IGF-1 and lead to HER2 phosphorylation." (PMID 36291900, 2022). "IGFBP3-mediated activation of the EGFR and IGF1R has been suggested previously in breast cancer epithelial cells, in which treatment of cells with IGFBP3 resulted in ligand-stimulated EGFR and IGF1R activation and subsequent downstream DNA synthesis." (PMID 36497022, 2022). "In lung and breast cancer animal models, citrate treatments inhibited tumor growth by suppressing the insulin-like growth factor type 1 receptor (IGF-1R)/AKT/PTEN/eukaryotic translation initiation factor 2A (eIF2A) pathway." (PMID 35884416, 2022). "In breast cancer cells, t-DARPP protein associates with IGF-1R resulting in increased AKT phosphorylation and greater glycolysis." (PMID 34675407, 2022). "Further comparison was conducted focusing on the general data, clinical stage, tumor histological grade, molecular classification and prognosis, and the expressions of IGF-1R and Ki-67 in breast cancer tissue between groups." (PMID 35035440, 2022). "TRIP-Br1-mediated higher IR/IGF1R ratio enhanced the proliferation and survival of breast cancer cells." (PMID 35710446, 2022). "In this mini review, we summarize the phenotypes of existing mouse models of modified IGF1R expression in mammary tissue and discuss observations made using human breast cancer data." (PMID 35784559, 2022). "To model human breast cancers with low IGF1R expression, we also generated a mammary luminal epithelial lineage-specific Igf1r knockout mouse driven from a tamoxifen-inducible Keratin 8 (K8)-Cre, referred to as the K8iKOR line." (PMID 36568144, 2022).
breast cancer (continued). "A further cancer vaccine study demonstrated that the VLPs, obtained by human parvovirus B19 chimeric VP2 proteins displaying two epitopes of the insulin-like growth factor-1 receptor (IGF-1R), were effective against breast cancer in the animal model." (PMID 35214685, 2022). "Integration of human patient data with single cell sequencing data from mouse tumors revealed similar pathways necessary for promoting metastasis in basal-like mammary tumors with reduced signaling or expression of IGF1R." (PMID 36568144, 2022). "In particular, homologs AKT1, AKT2, ERBB2, FGFR2, and PIK3CA in CGC play important roles in breast cancer progression, mediating breast cancer risk, corresponding to the driver candidates RPS6KA1, SGK1, PTK2, IGF1R, PIK3CB, and PRKDC predicted by DriverMP." (PMID 38091511, 2022). "Trastuzumab resistance was also partly mediated by the IGF-1R pathway in HER2(+) breast cancer cells." (PMID 36017326, 2022). "Early studies investigating IGF1R expression in human breast cancer patients produced conflicting reports as to the prognostic value of IGF1R expression in patient samples." (PMID 35784559, 2022). "Consistent with its tumor suppressor role, wild-type BRCA1 was shown to repress IGF1R gene transcription and promoter activity as well as endogenous IGF1R levels in breast cancer cells." (PMID 35432218, 2022). "IGF-1 system, consisting of IGF1, IGF-binding proteins (IGFBPs), and IGF1R, acts as one of the most upstream signaling pathways to regulate various pathophysiological processes during tumorigenesis including breast cancer." (PMID 36042202, 2022). "We have previously identified a novel human monoclonal antibody (mAb), m708.5, which neutralizes both human IGF-I and IGF-II, and potently inhibits phosphorylation of the IGF-1R and the IR in breast cancer cells." (PMID 35399718, 2022). "Telaprevir prevents the growth of breast cancer cell lines by interfering with the IGF‐1R pathway leading to FOXA1 down‐regulation, ERα inhibition, and induction of apoptotic cell death." (PMID 36056637, 2022). "IGF-1, produced by adipocytes, binds to IGFI on cancer cells and endorses cancer cell proliferation through PI3K/AKT and MAPK systems, whereas inhibition of IGF-1R abolishes the tumor promoting effect of adipocytes on breast cancer cells." (PMID 36077676, 2022). "An independent study in breast cancer cells has shown that IGFBP-6 silencing by shRNA induced expression of genes encoding miR-100 and let-7a, which are known to target IGF-2, IGF1R and INSR." (PMID 35597813, 2022). "A small-molecule PRCP inhibitor blocked IGF1R/HER3 signaling in breast cancer cells, and enhanced the responsiveness of human ER+ breast cancer tumors in mice to endoxifen, an active metabolite of TAM." (PMID 36332175, 2022). "Insulin-like growth factor-1 receptor (IGF-1R), a transmembrane tyrosine protein receptor, is highly expressed in nervous system malignancies, hepatocellular carcinoma, breast cancer, adrenocortical tumors and lung cancer." (PMID 35035440, 2022). "A recent pre-clinical study provided evidence that co-treatment of breast cancer cells with AEW541 (a selective IGF1R inhibitor) along with gemcitabine (a chemotherapeutic drug) improved the treatment efficiency." (PMID 36479090, 2022). "Future therapies that preserve normal glucose uptake and reduce peripheral glucose levels will prevent compensatory stimulation of the IGF-1R pathway in breast cancers." (PMID 36556357, 2022). "Historically, the body of literature surrounding the insulin-like growth factor type 1 receptor (IGF1R) has described a largely pro-tumorigenic role in breast cancer cells and in several transgenic or xenograft mouse models of breast cancer." (PMID 35784559, 2022). "Transfection of a BRCA1 expression vector in breast cancer cells led to a marked reduction in endogenous IGF1R levels and promoter activity." (PMID 36479090, 2022).